NOS2 (nitric oxide synthase 2)
Diseases named in the same sentence as NOS2 in open-access papers (continued):
Sharing a sentence is not in itself a finding about the gene and the disease.
tumor (continued). "COX2 activity is enhanced by NOS2-derived NO, which promotes angiogenesis and cell differentiation and tumor growth, invasion and metastasis potential." (PMID 34200849, 2021). "Using a murine model, it was shown that irradiated prostate tumors and TAMs had increased expression of Arg1 and Nos2, and the crosstalk between malignant cells with TAMs conferred increased aggressiveness to the tumor." (PMID 34960055, 2021). "In the preclinical study, IFN-β can increase the tumor infiltration of regulatory T cells via NOS2, resulting in immunosuppression and AR." (PMID 34194441, 2021). "iNOS expression correlates with VEGF and together is very vital for tumor growth; high levels of NO produced by the NOS2 triggers the angiogenesis process in the tumors by regulating the VEGF expression." (PMID 33815659, 2021). "G-CSFR−/− macrophages demonstrated increased NOS2 expression and tumor killing ability, while the addition of G-CSF to wildtype (WT) macrophages led to decreased NOS2 activity and increased IL-10 production to promote a pro-tumorigenic phenotype." (PMID 33036138, 2020). "We used RT-PCR and western blotting to determine the relative expression levels of ARG1 and NOS2 in HLA-DR-mononuclear cells in the peripheral blood and tumor tissues of GC patients." (PMID 32415175, 2020). "According to GeneCards, NOS2 is a reactive free radical that acts as a mediator in some biological processes, such as a neurotransmitter, an anti-microbial, and an anti-tumor." (PMID 32986356, 2020). "Next, we determined the relative expression levels of ARG1/NOS2 in those circulating and tumor-infiltrating MDSCs by qRT-PCR and Western blotting." (PMID 32415175, 2020). "Specifically, current research indicates that one of the three forms of NOS, iNOS or NOS2, is most likely responsible for the tumor promoting and tumoricidal effects of NO." (PMID 32340209, 2020). "In fact, the role of NOS2 in the cancer process is very complex; hence we can talk about it as a tumor promoter and suppressor at the same time." (PMID 33374571, 2020). "Previous studies have shown that there is a large amount of ARG1 and NOS2 in MDSCs under tumor conditions and that these factors can inhibit the function of T cells, thereby creating an important mechanism for immune-avoidance." (PMID 32415175, 2020). "Adoptive transfer of G-CSFR−/− into colon or pancreas tumor-bearing mice led to decreased tumor growth and increased NOS2 and apoptosis." (PMID 33036138, 2020). "Similar to what occurred in KPC‐conditioned media treated primary microglia, we observed increased expression of Il‐1b and Arg1 in the hypothalami of tumor‐bearing animals compared to sham animals, whereas there was decreased expression of Nos2 and Tmem119." (PMID 32039522, 2020). "The 3-NT is considered a footprint of NOS2 activity, and NOS2 expression in tumors of the digestive tract is elevated." (PMID 33167555, 2020). "When analyzing spleen cells from tumor-bearing mice at day 15–17 p.i., we detected similarly significant changes in Tnfα, Ifnγ, and Nos2 expression and a significant increase in Sgk1 expression." (PMID 31214164, 2019). "While PD-L1 was not involved in secondary resistance to anti-PD-1 mAb, reducing NOS2 with L-NAME or a genetic knockout improved long-term tumor control by PD-1 blockade in several tumor models." (PMID 31481761, 2019). "NOS2 is expressed by various cell types involved in inflammation, including neutrophils, M2 macrophages, MDSCs, DCs, NK cells, endothelial and tumor cells." (PMID 32039024, 2019). "Sustained IFNβ transcription was observed in resistant tumors, in turn inducing PD-L1 and NOS2 expression in both tumor and dendritic cells (DC)." (PMID 31481761, 2019). "M1 macrophages also express higher levels of Nos2, Cxcl10, and Irf7 and expression of each of these genes increased in the injected tumor in response to combination treatment." (PMID 31921384, 2019).
tumor (continued). "Both the tumor and leukocyte cell fractions upregulate Nos2, the latter being mostly represented by CD11c+IAIEhi cells, with DC being the most prominent producers in vitro." (PMID 31481761, 2019). "It seems NOS2 affects multiple oncogenic pathways that simultaneously affect tumor proliferation, angiogenesis, chemoresistance, and cell migration." (PMID 31681611, 2019). "A chronic PD-1 blockade progressively induced IFNγ and IFNβ transcription in the TME, with both IFNs in turn triggering PD-L1 and NOS2 expression on both tumor cells and leukocytes." (PMID 31481761, 2019). "Recently, in a model system of GBM—non-ionizing photodynamic therapy—the reported findings indicated that suppressing NOS2 expression markedly increased the efficacy of anti-tumor therapy." (PMID 30227679, 2018). "TAMs from SNAIL1 depleted tumors displayed increased expression of M1-like/anti-tumor genes like Ifna1, Il12a, Il6, Nos2, and Ifnb1." (PMID 29593211, 2018). "The pro-inflammatory mediators directly correlate with inducible nitric oxide synthase (NOS2), which is an emerging biomarker of aggressive tumours that predicts poor survival in patients with elevated tumour NOS2 expression." (PMID 30558287, 2018). "The frequencies of tumor-associated immunosuppressive factors, including the COX2, IL-10, NOS2 and IDO1 mRNA was abrogated by the addition of COX2 inhibitor during the generation of CM from cancer ascites cells." (PMID 29163789, 2017). "We demonstrated that mMDSC mediated expression of NOS2 is partially responsible for the induction EMT phenotype in tumour cells." (PMID 28382931, 2017). "Many suppressive pathways, including the COX2, IL-10, NOS2 and IDO1 mechanisms described here, have been implicated in tumor-associated immune dysfunction within the human TME." (PMID 29163789, 2017). "γδ T cells in Ret mice lysed less efficiently tumor cells, and produced less IFN-γ than their counterparts in Ret mice deficient for NOS2." (PMID 27812136, 2016). "To examine the effect of NOS2/NO signaling on the tumorigenic potential of pancreatic cancer cells, we isolated primary tumor cells from KPC and NKPC mice." (PMID 27367029, 2016). "The results are also consistent with reduced expression of the antiapoptotic genes Birc3, Birc5 and Nos2 in livers from TLR4-/- mice suggesting that TLR4 mediates survival ligands to tumor initiating cells." (PMID 27391331, 2016). "Correlation analysis demonstrated tumor expression of NOS2 is negatively correlated with PDLIM2 levels (r2=0.2082; P=0.0328) in ovarian cancer specimens, suggesting a functional link between the two factors." (PMID 26593252, 2016). "Consistent with the data from the RNAseq analysis, three HER2 fusion genes—ZNF207 (exon 1–2)/HER2 (exon 18–30), MDK (exon 1–4)/HER2 (exon 11–30), and NOS2 (exon 1–2)/HER2 (exon 2–30)—were further confirmed in these tumor DNA samples." (PMID 25889497, 2015). "To determine if NOS2 plays a major role in the response to CTLA-4 blockade, we treated mice with established AB1-HA tumours with anti-CTLA-4 in combination with competitive NOS2 inhibitor L-NG-nitroarginine." (PMID 26193793, 2015). "In fact, VSSP treatment not only prevented up-regulation of Arg1 and Nos2 on tumor-induced MDSCs but also reduced MDSCs-mediated down-regulation of CD3ζ chain on antigen-specific CD8+ T cells." (PMID 24829762, 2014). "More studies are necessary to establish the role of the path ON/NOS2 in tumor genesis and evolution and to determine the usefulness of NOS2 inhibitors as chemo-prevention medication." (PMID 24316703, 2014).
tumor (continued). "Sildenafil, a phosphodiesterase-5 inhibitor, reduced arginase 1 and nitric oxide synthase-2 expression in a mouse tumor model." (PMID 24995313, 2014). "The complexity and the heterogeneity of the NOS2 expression in tumors and within a same tumor has been found in the literature; the same finding was reported when other cancerization markers have been used." (PMID 24316703, 2014). "Tumor epithelial cords were positive for NOS2; the degrees of expression were variable, in agreement with previous studies." (PMID 24316703, 2014). "The present study not only analyzed NOS2 expression in tumor tissues but also demonstrated its activity in the surrounding normal tumor epithelium." (PMID 24316703, 2014). "Another newly characterized population of cells called myeloid-derived suppressor cells (MDSCs) are recruited by inflammatory mediators, which inhibit the anti-tumor responses and release pro-tumor molecules, like, NOS-2 and TGF-β." (PMID 24782866, 2014). "In the murine subcutaneous tumor-formation model, NEAPP-AM injection resulted in an average inhibition of the NOS2 cell-inoculated tumor by 66% (P<0.05) and NOS2TR cell-inoculated tumor by 52% (P<0.05), as compared with the control." (PMID 24367486, 2013). "The plasma-activated medium induced a significant inhibition of tumor growth in mice bearing both parental NOS2 and chemoresistant NOS2TR cells." (PMID 24367486, 2013). "NEAPP-AM injection resulted in an average inhibition of NOS2 cell-inoculated tumor weight by 66% (P = 0.017) and NOS2TR cell-inoculated tumors by 52% (P = 0.014), as compared with the control." (PMID 24367486, 2013). "Very often a high intensity of NOS2 immunopositive precipitate accumulated close to the luminal plasmalemma of the vascular EC in the tumor growth region, indicating the elevated tissue levels of NO and ET-1." (PMID 23691268, 2013). "The presence of NOS2 immunopositive hepatocytes and myofibroblast-like cells is also seen throughout the tumor growth area." (PMID 23691268, 2013). "Subcutaneous tumor formation was observed at least approximately 10 days after the inoculation of mice with NOS2 or NOS2TR cells." (PMID 24367486, 2013). "Our report indicated that NOS2 and ET-1 expressions are linearly correlated with the degree and nature of tumor growth." (PMID 23691268, 2013). "The calculated tumor volumes on day 28 were 300±136 (mm3 ± SD) and 163±91 in the NOS2 and NOS2TR control groups and 55±60 and 104±66 in the NOS2 and NOS2TR groups treated with NEAPP-AM, respectively (p = 0.0014 and 0.097, respectively)." (PMID 24367486, 2013). "The examination of tumor-relevant changes in developing cerebellum as a consequence of impaired Nos2 activity and hence NO signaling surprisingly revealed a decreased proliferation of GCPs in the cerebellum of Ptch1+/+ Nos2−/− mice." (PMID 22438824, 2012). "The amounts of CD163+ cells at the tumor front, however, were frequently higher than that of NOS2+ cells." (PMID 23077543, 2012). "Differential expression of selected candidate genes was validated by qRT-PCR on an expanded, partially overlapping tumor set of seven Ptch1+/− Nos2+/+ versus seven Ptch1+/− Nos2−/− MB samples." (PMID 22438824, 2012). "Here, we report on the generation of Ptch1+/− Nos2−/− mice to investigate the impact of Nos2 on tumor development in Ptch1 hemizygous mutant mice." (PMID 22438824, 2012). "A strong inverse correlation to tumor stage was found for both NOS2 (P<0.0001) and CD163 (P<0.0001) infiltration." (PMID 23077543, 2012). "The inducible enzymes COX2 and NOS2 were overexpressed in peritumor and tumor tissue from GBM and, in the case of cancer stem cells, COX2 expression was increased by hypoxia." (PMID 21489226, 2011).
tumor (continued). "By contrast, NOS2 mRNA showed a pattern of increasing up-regulation from peritumor to tumor tissue compared to the host tissue." (PMID 21489226, 2011). "Cytoplasmic and nuclear staining for COX-2 and NOS-2 was also observed both in the tumor and non-tumor hepatic cells." (PMID 21152281, 2010). "Spatially, NOS2/COX2 niches at the tumor-stroma interface and within immune deserts generate gradients of NO, PGE2, oxygen, and metabolites that partition tumors into microdomains with distinct metabolic states, immune composition, and therapeutic vulnerabilities." (PMID 42248132, 2026). "Integrating these insights with Hanahan's updated hallmarks of cancer, we propose that NOS2-derived NO functions as a node synchronizing deregulated energetics, inflammation, immune evasion, plasticity, and therapy resistance within the tumor microenvironment (TME)." (PMID 42248132, 2026). "Thus, the spatial relationship between tumor NOS2/COX2 expression and CD8+ TEff cells is a key predictive factor of antitumor immune response." (PMID 40663402, 2025). "Given the strong association between the NOS2/ARG axis and leukocyte infiltration, we hypothesized that the NOS2/ARG axis may contribute to tumor progression by influencing the composition and polarization of infiltrating immune cells." (PMID 41573553, 2025). "Furthermore, the expression levels of TNF-α, IL-6, IL-1β, and NOS2 in tumor tissues were enhanced following CIRT treatment compared to the control group (p < 0.001)." (PMID 40917841, 2025). "Interestingly, we found that the expression of the anti-tumor inflammatory gene Nos2 was increased in both the H1-PD and H2-PD mice, but this was more striking in the H2-PD mice." (PMID 40443227, 2025). "However, NOS2 was shown to inhibit tumor growth and induce tumor cell death both in vitro and in vivo, potentially through suppression of the NF-κB pathway." (PMID 41425595, 2025). "Our analysis of the TME shows that intratumoral T cell activation leads to neutrophil recruitment and upregulation of nitric oxide synthase 2 (Nos2) which could lead to tumor killing by bystander neutrophils." (PMID 40280970, 2025). "Interestingly, we observed TReg clusters that aligned with high CD8+ T cell densities in tumors from alive patients with low NOS2/COX2 tumor expression." (PMID 40663402, 2025). "In addition, CD8+ TRegs were elevated in stromal lymph aggregates, while CD4+ TRegs were also elevated at NOS2+ tumor edges when compared with tumor satellite and/or core regions." (PMID 40663402, 2025). "Taken together, both 1 and its glucoside 7 displayed particularly robust inhibitory effects against ARG1 mRNA expression and induced a significant increase in NOS2 mRNA expression, suggesting their capacity to alter the tumor-suppressive phenotype of RAW264.7 cells." (PMID 40430260, 2025). "The distribution of lymphoid populations formed a gradient ranging from stroma-restricted lymphoid aggregates composed of both CD3+CD4+ and CD3+CD8+ T cells to single CD3+CD8+ T cells that had penetrated NOS2+/– edges and into the tumor satellite and core regions." (PMID 40663402, 2025). "These distinct phenotypes suggest that tumor NOS2/COX2 distributions could have a role in the progression and maintenance of the tumor’s immune deserts and TEff cell exclusion." (PMID 40663402, 2025). "So, a dual therapeutic approach combining KRAS inhibitors with NOS2 inhibitors could enhance the anti-tumour response." (PMID 40567499, 2025). "Because IFNγRKO tumours are characterised by an increase in monocyte-derived NOS2+ macrophages, we hypothesised that macrophages controlled IFNγRKO tumour growth through NOS2-induced nitric oxide (NO), which can exert anti-tumour effects." (PMID 39746898, 2025).
tumor (continued). "While NOS2 and COX2 affect the whole tumor landscape, they also influence specific tumor regions, including large tumor nests, lymphoid aggregates, tumor edge, tumor core, and tumor satellites, which are affected differently by the spatial configuration and distribution of TEff/NOS2/COX2 phenotypes." (PMID 40663402, 2025). "Regarding IFN-β, sustained signaling has been implicated in acquired immunotherapy resistance by inducing PD-L1 and NOS2 expression in both tumor and dendritic cells, leading to the accumulation of regulatory T cells (Tregs) and myeloid cells and resulting in acquired resistance to ICB." (PMID 41205596, 2025). "Herein, immunosuppressive mechanisms of tumor NOS2/COX2 expression were spatially explored using multiplex immunofluorescence imaging of 20 ER– tumors from patients who succumbed to disease (deceased; n = 10) versus those who survived (alive; n = 10) at 5 years after diagnosis." (PMID 40663402, 2025). "Notably, murine Nos2 expression in tumor tissues was altered by PCCA, while human NOS2 expression remained unaffected." (PMID 39744168, 2025). "Tumor NOS2 expression was generally localized at NOS2+ edges and tumor satellite regions." (PMID 40663402, 2025). "This study aimed to evaluate the association between NOS2/ARG1 expression and systemic immune cell ratios with local tumor immune infiltrates (TILs, TAMs) and to assess their prognostic significance for response to cetuximab-based chemotherapy and patient survival." (PMID 41573553, 2025). "The potential association between sGCα1 and tumor progression was previously reported by Eggen and colleagues who demonstrated that NOS2, sGCα1, and sGCα2 expression correlated with tumor growth in tissue samples from patients with early-stage cervical carcinoma." (PMID 39337539, 2024). "In addition, stroma-restricted CD8/CD4 T cells supply IFNγ and TNF/IL1 to the tumor nest, which further promotes tumor NOS2/COX2 expression at the tumor margin that leads to the formation of metastatic and CSC niches that are regionally distinct." (PMID 39356141, 2024). "Interestingly, elevated tumor expression of NOS2 and COX2 predicts poor survival in estrogen receptor–negative (ER–) patients." (PMID 38912586, 2024). "Moreover, the results herein show an important spatial correlation, in which the stroma restriction of CD8+ T and increased tumor NOS2 and COX2 expression correlated with poor survival." (PMID 39356141, 2024). "In comparison, human NOS2 expression was detected under the same conditions in vitro but was considerably lower (3%–5%) when compared with Nos2 expression (40%–100%) in murine 4T1 tumor cells." (PMID 39356141, 2024). "Besides, MDSCs also highly express NOS-2, not only decompose arginine but also produce NO to impair anti-tumor effect of T cells." (PMID 38218942, 2024). "Taken together, tumor NOS2 and COX2 expression collaborates during the metastatic process, which may involve at least in part the upregulation of EpCAM expression." (PMID 39356141, 2024). "Moreover, they demonstrated that tumour‐secreted factors modulated metabolism via nitric oxide synthase 2 (NOS2), negatively impacting myoblast differentiation." (PMID 38644205, 2024). "Importantly, these NOS2+ tumor satellites exhibit increased elongation and migration consistent with increased tumor metastatic potential." (PMID 39356141, 2024). "Although NOS2/COX2 regions do not span the entire tumor and are not linked to a broader immune desert, these small focal points suggest a mechanism of cancer progression associated with poor outcomes." (PMID 38892290, 2024). "In addition, arginine can produce NO under the catalysis of nitric oxide synthase-2 (NOS-2) in tumor and macrophage." (PMID 38218942, 2024). "Furthermore, we assessed the relative mRNA levels of S100A8, S100A9, Nos2, and Arg1 in the tumor tissues." (PMID 38952044, 2024).